CD44 (CD44 molecule (IN blood group))
Diseases named in the same sentence as CD44 in open-access papers (continued):
Sharing a sentence is not in itself a finding about the gene and the disease.
tumor (continued). "In CD44+/CD133 + MiaPaCa2 cells, a decrease in miR-34 presence was combined with a rise in Notch/Bcl-2 and a higher concentration of tumor stem/progenitor cells, tumor sphere-forming cells, and tumor initiating cells." (PMID 38725047, 2024). "The role of CD44 in maintaining stemness and the CSC function in tumor progression is accomplished by binding to its main ligand, hyaluronan (HA)." (PMID 38672650, 2024). "HA is a ligand for various cell surface receptors (CD44, LYVE-1, RHAMM, and HARE) that are overexpressed in tumor cells and nanogels preferentially accumulate in tumor tissues due to the enhanced permeability and retention (EPR) effect." (PMID 39339063, 2024). "Western blot analysis of tumor tissue lysates showed elevated OPN, PD-L1, p21Cip1, c-Myc, survivin, CD44, and ISG15 upon irinotecan treatment." (PMID 39456585, 2024). "CD44 and CD24 are important and widely recognized BCSC surface markers which are found in many tumor types and are often used together or in combination with other putative markers to isolate stem cells from solid tumors." (PMID 39469631, 2024). "Injection of a CD44 mAb-IR700 dye conjugate (anti-CD44-IR700) in mice bearing oral SCC CD44+ MOC1 and MOC2 tumors significantly inhibited tumor growth and prolonged survival." (PMID 38612911, 2024). "The results showed that the expression of CD44, CD166, CD90 and CD87 stemness markers in tumor cells increased with the elevation of IRGS." (PMID 38243040, 2024). "Manual gating confirmed these findings and showed that CD86 blockade in the context of RT increased the frequency of CD44+TCF-1– cells among CD8+ T cells in both the TdLN and tumor." (PMID 38349740, 2024). "The interaction between SPP1 and CD44 is thought to inhibit the activation of CD8 + T cells, promoting tumor immune tolerance and immune escape." (PMID 38806553, 2024). "Tumor immune dysfunction and exclusion (TIDE) was used to evaluate the predictive ability of CD44 for immune checkpoint blockade (ICB) responses." (PMID 38590654, 2024). "We subsequently examined the expression of SRGN and CD44 in cell line, and found that SRGN was mainly expressed in tumour cells, whereas CD44 was detected in fibroblasts." (PMID 38862740, 2024). "In tumor resection specimens of EC patients, the overall percentages of FAK+, CD44+, HIF-1α+, and Ki67+ cells were higher in tumor nests than in the tumor stroma, with the outcome for Ki67+ cells reaching statistical significance (p < 0.001)." (PMID 38727811, 2024). "Our data suggest that the tumor endothelial CD44-mediated internalization and transcytosis play a more important role than either EPR or tumor cell CD44-mediated targeting in the total amounts of NPs accumulated in the tumor tissues." (PMID 38177179, 2024). "They explained that tumors with greater DOI showed stronger CD44 expression suggestive of EMT and CSC signaling enabling the tumor to invade and metastasize to the nearby lymph node." (PMID 37593530, 2023). "Tumor sections were stained using immunohistochemistry for proliferation markers Ki67, RCN3, and CD44." (PMID 37046668, 2023). "The adhesion molecules on the surface of CTCs, such as CD44 and MUC1, can bind to selectins so that the weak adhesion between tumor cells and the endothelium is established." (PMID 37108248, 2023). "In contrast, memory T-cell markers and costimulation makers, including CD27, CD44, CD45RO, ICOS, and 4-1BB, were lower within the tumor core of liver metastases, indicating decreased immune activity, possibly contributing to decreased lymphocyte infiltration." (PMID 37768208, 2023). "Further in vitro research reported that miR-143 and miR-145 hamper the tumor sphere formation by inhibiting stemness factors such as CD133 and CD44 in PC-3 PCSs." (PMID 36969009, 2023). "HA-AuNR accurately targets tumor tissues (because the tumor cells express CD44 at a high level) under NIR laser for PTT, stimulating the ICD of tumor cells and anti-tumor immunity." (PMID 37600822, 2023).
tumor (continued). "It is found that miRNA-34a acts as a tumor suppressor miRNA through Neurogenic Locus Notch Homolog Protein 1 (NOTCH1) and CD44 signaling to induce apoptosis and suppress tumor proliferation, migration, and growth in Triple-Negative Breast Cancer (TNBC) cells." (PMID 37107631, 2023). "Thus, the targeted inhibition of CD44/SLC7A11 may make tumor cells prone to ferroptosis." (PMID 36672372, 2023). "Restoring miR-34a expression inhibits CD44 and CD133 expression in vitro and suppresses tumor formation in vivo." (PMID 37173787, 2023). "This phenomenon is facilitated by the upregulation of CD44, acting as a receptor for OPN, thereby promoting the expansion of cell populations that facilitate tumor progression and immune resistance." (PMID 38332915, 2023). "The tumor-seeding potential in immunocompromised (NOD-SCID) mice and DEGs in the tumors were also assessed along with the intra-tumor (CD44+/CD24-) expression using flow cytometry." (PMID 37298091, 2023). "Recently, it has been demonstrated that HA interaction with both CD44 and TLR4 sustains colon tumorigenesis, by promoting tumor growth in mice." (PMID 37568628, 2023). "The xenografts derived from CD44+ and CD44- cells showed a predominant ADRN identity, demonstrating the strong ability of the tumour microenvironment (TME) to drive NB cells towards ADRN differentiation." (PMID 37849756, 2023). "Enrichment of T-cell markers (CD3, CD4), macrophage markers (CD68, CD168), immune checkpoints (CD27 and V-domain Ig suppressor of T-cell activation [VISTA]), CD44 and CD45 were seen in the stroma relative to the tumour." (PMID 37835491, 2023). "Aptamers against EpCAM, CD44, and CD133 have been used widely as targeting ligands to guide therapeutic agents to CSCs in different tumor types." (PMID 36969696, 2023). "Mechanistically, MIF independently interacts with CD74 in a hetero-complex with CD44, CXCR2, CXCR4, and ACKR3 to initiate downstream MAPK and PI3K pathways, all of which influence tumor initiation, growth, and metastatic dissemination." (PMID 38065972, 2023). "One BCSC state is mesenchymal-like (CD44+/CD24−) with low proliferative activity and located mainly at the tumor-invasive edge." (PMID 38090567, 2023). "After analyzing the number of tumor stem cell–like cells in tumor tissue, THC can reduce the number of cells (CD44+/CD24−)." (PMID 36707875, 2023). "In a mouse transplantation model, the expression levels of cancer stem cell markers, such as CD44 and CD133, were upregulated, and tumor growth was promoted in SCC25 cells by EBV infection." (PMID 37762374, 2023). "EBA treatment induced apoptosis and a sharp decline in the expression of the BCSC markers ALDH1, CD44 and CD49f, suggesting that EBA targets BCSC-like cell populations while reducing tumor bulk." (PMID 37185776, 2023). "Studies have demonstrated that an interaction between CD44 and SPP1 induces cell signaling and modulates tumor cell activation, motility, and adhesion, resulting in cancer progression and metastasis." (PMID 38235128, 2023). "Here, we found that BMI1, CD44, SOX2, OCT4, UBE2C, CXCR4 CSCs marker genes are significantly upregulated, while IGF1-R, KLF4, ALDH1A1, CD133, FAM3C are downregulated in the tumor core vs healthy mucosa of 24 patients with OSCC." (PMID 38096163, 2023). "This protein subcomplex was identified in two different types of PCSCs, derived from PASC and PDAC neoplasms, which were phenotypically sorted based on their surface expression of CSC markers, including ABCG2, CD44, and CD133." (PMID 37709746, 2023). "We recently reported that patients with GBM showing high CD44 expression in the tumor periphery show significantly shorter survival in terms of both PFS and OS than those showing low CD44 expression." (PMID 37835592, 2023). "Aptamers against CD44, CD133, and EpCAM have been tested as targeting ligands in a variety of tumor types." (PMID 36969696, 2023).
tumor (continued). "Functionalization of mCNTs with anti-CD44 antibody, which recognizes GBM cell surface–enriched antigen CD44, increases mCNT recognition of cancer cells, prolongs mCNT enrichment within the tumor, and enhances therapeutic efficacy." (PMID 36989359, 2023). "IHC staining of tumor sections revealed that the levels of ALDH1, CD44, CD133, SOX2, Notch1, EZH2 and CCND1 were downregulated in CDK5RAP2-knockdown tumors." (PMID 36774351, 2023). "Prior to investigation of anti-tumor activity of Ad-CD44-N-HIF-3α4 in MDA-MB-231 (TNBC) cells, we confirmed the expressions of CAR and CD44 on the cell surface and the induction of HIF-1α and VEGF mRNA by hypoxia." (PMID 37064130, 2023). "In our study, we examined the levels of three micro RNAs: one oncogenic (miR–21) and two tumor suppressors (miRNA-133 and miRNA-491) in CD44+ and CD44− cells." (PMID 36902135, 2023). "CD44 was the most widely known receptor of SPP1, mainly found on T cells (black box) and tumor cells (black arrow)." (PMID 37336873, 2023). "Specifically, we observed more CD4+ and CD8+ T cells, including increased numbers of activated central memory (CD44+CD62L+) and naive (CD44− CD62L+) T cells, after tumour cell engraftment at ZT9." (PMID 36470303, 2023). "Of note, the CD28+ cluster was detected also in the tumor, and accordingly it was enriched by ITGA4 (CD49), CCR5 and CD44, all contributing to CD8+ T-cell infiltrative capacity." (PMID 37898752, 2023). "CD44, CD45, and HAVCR2 acted as receptors, indicating an important role of endothelial cell-derived LAGALS9 in the LN metastasis of tumor cells." (PMID 38065972, 2023). "As binding between CD44 and HA plays a key role in the migration of BMSCs, the hyaluronic acid synthase-3 (HAS3) expression was compared among the various tumor cells." (PMID 37370133, 2023). "Quantitative confocal immunofluorescence analysis showed that tumor stem cell marker CD44 was significantly decreased, and the apoptotic marker BID protein expression was increased in CHCP-treated tumor samples compared to untreated tumor samples." (PMID 37509349, 2023). "Treatment of mice with anti-CD44 mAb, blocking a major OPN receptor, significantly reduced tumor growth in vivo." (PMID 37398648, 2023). "CD4+ and CD8+ effector T lymphocytes (CD3+/ CD44+/ CD62L−) were measured in spleen, DLNs, and tumor tissues, considering their relevance in the elimination of solid tumors and their value for tumor prognosis." (PMID 37736849, 2023). "Inactivating c-Met by genetic knockdown or pharmacologic treatment not only reverses the EMT process but also diminishes the CD44+CD133− CSC population in radioresistant HNSCC cells, leading to an overall reduction in tumor development and progression." (PMID 37089864, 2023). "The mechanistic basis for the role of the hyaluronan/CD44 axis in cancer involves its contribution to cell adhesion, migration, survival, proliferation, CSC maintenance, and modulation of the tumor microenvironment." (PMID 37958796, 2023). "According to the current studies, there are 7 HA receptors, CD44, RHAMM, TLR2, TLR4, LYVE, LAYN and STAB2, which participate in connecting extracellular signal and intracellular signalling in tumor diseases." (PMID 36698043, 2023). "CSCs (CD44+CD24+) and NSCCs (CD44−CD24−) were then inoculated into the abdomen of nude mice, and the tumor weight and volume were found to be increased in the presence of CSCs compared with NSCCs." (PMID 37005676, 2023). "Effector memory T cells (CD3+CD8+CD44+CD62L–) were proved to induce effective immune protection and play an important role in killing tumor cells." (PMID 37700338, 2023). "Cancer stem cells, characterized as CD44+/CD24-/low expression and high ALDH activity, possess tumor initiation capacity, unlimited self-renewal competence and the ability of differentiating into heterogeneous cells." (PMID 36594100, 2023). "Tumor-suppressive CM was enriched with MSN, whose anti-tumor action was mediated by CD44, a cell-surface adhesion receptor." (PMID 37699930, 2023).
tumor (continued). "The use of CD44 as an HNSCC CSC marker is highly discussed in the literature, and its specificity appears to depend on the original tumor tissue." (PMID 36864434, 2023). "A variety of protein partners can interact with CD81, either to regulate attachment and uptake of viruses (HCV E2, claudin-1, IFIM1) or to contribute to tumor growth and dissemination (CD19, CD44, EWI-2)." (PMID 37046846, 2023). "Not only that, they also found that renal CSCs were positive for C-X-C motif chemokine receptor 4 (CXCR4), mesenchymal-epithelial transition factor (MET) and homing cell adhesion molecule (CD44), which accounted for an average of 2.2% of the total tumor cells." (PMID 37025584, 2023). "Following initiation tumor rejection, sgSocs1 OT1s made up 7% of blood CD8+ T cells, with a CD44+CD62L+ phenotype reflecting Tcm cells." (PMID 38099496, 2023). "Among those, we focused on auto-/paracrine TGF-β1 signaling, the interaction between CD44 and extracellular hyaluronic acid, and matrix metalloproteinases (MMP)-mediated remodeling of the tumor microenvironment." (PMID 37996600, 2023). "Various factors including cytokines, non-tumor cells, and oxygen concentration in the TME can affect the activity of CD44 signaling pathways." (PMID 37835592, 2023). "Similar to results when co-cultured with tumor cells, pre-treatment with AG1 resulted in increased proportions of CD44 + CD62L + cells and TCF1 + cells prior to adoptive transfer." (PMID 37790365, 2023). "CD44, a well-known cancer stem cell (CSC) biomarker, is expressed on leukocyte and tumor cells and involved crucially in inflammatory leukocyte homing, tumorigenesis and cancer progression." (PMID 36768572, 2023). "It is interesting to note that co-treatment of casticin and agomir-148a-3p showed the strongest inhibitory effect on the tumor weight and volume, the downregulation of DNMT1 and CD44 mRNAs, and the highest upregulation of miR-148a-3p." (PMID 37304067, 2023). "The percentages of BCSC as well as expression of their markers, such as CD44, CD24, ALDH1, and CD133, are tumor-subtype dependent." (PMID 37445860, 2023). "In vivo studies showed that nWdl effectively reduced tumor volume and BCSC population (CD44+/CD24−/low) in xenograft models." (PMID 36899854, 2023). "The main ligand of CD44 is hyaluronic acid (HA), an abundant component of the extracellular matrix (ECM) expressed by stromal and tumor cells." (PMID 36831554, 2023). "Naïve T cells and CD44+CD62L+ Tcm cells were significantly reduced after cryoablation, whereas CD44+CD62L− Tem cells were increased in both tumours and spleens." (PMID 37157934, 2023). "Clinically, circulating-tumor cells (CTCs), which express EpCAM, MET, and CD44, identify a subset with increased metastasis-initiating phenotype, suggesting that CD44v6 plays an important role in cancer-initiating cell property cooperating with MET." (PMID 36835416, 2023). "Flow cytometry analysis of the BCSC population and tumorsphere growth assay also revealed that downregulation of SRC dramatically reduced the percentage of CD44+/CD24−/low population, and the tumor cell self-renewal ability." (PMID 36633714, 2023). "In particular, ablation of CD44 lowered the LDHA-to-LDHB ratio, promoting mitochondrial respiration, while overexpression of CD44 increased the LDHA-to-LDHB ratio, enhancing lactate glycolysis and the Warburg effect in tumor cells." (PMID 37894408, 2023). "Immunohistochemical analysis confirmed the expression of ALDH1A1, CD44, and EpCAM in both TN and NAT tumor tissues." (PMID 36400567, 2023). "Interestingly, the amount of CD44 in lipid rafts can vary in different cell types and can be displaced from these membrane domains upon E-cadherin expression, which negatively regulates HA–CD44 interactions and CD44-dependent tumor invasion and branching morphogenesis." (PMID 37894408, 2023).
tumor (continued). "CD44-mediated endocytosis of iron-binding hyaluronan has been observed in primary tumor cells, which have an increased need for iron during EMT and increase iron uptake by upregulating CD44-mediated endocytosis." (PMID 37736551, 2023). "To explore the effect of zyxin on tumor stemness, we overexpressed zyxin in N87 and MKN45 cells and analyzed expression levels of CD44 and OCT4." (PMID 37667739, 2023). "Various authors have described the main CSCs markers of CRC, such as LGR5, CD133, and CD44, by identifying them from CRC tumours and testing the different subpopulations that exist within the tumour." (PMID 36835258, 2023). "An analysis of 138 ovarian tissue specimens revealed that the co-expression of CD44 and myeloid differentiation factor 88 (MYD88) in patients with epithelial ovarian carcinoma correlated with tumour progression, metastasis, and recurrence." (PMID 38201468, 2023). "Based on the expression and biological localization analyses of L/R pairs, we identified two L/R pairs (LAMB3/CD44 and ANGPTL4/SDC1) with high reliability between tumor cells and PCs." (PMID 37138324, 2023). "CD44, ICAM1, and integrin alpha X (ITAX) are adhesion molecules that participate in cell-cell binding and interaction during inflammation or tumor." (PMID 36860851, 2023). "To assess the CSC property within the tumor cells, we used flow cytometry to determine the CD44 and CD24 distribution in the primary orthotopic tumor (SQ mammary fat) and metastatic lung lesions." (PMID 37298091, 2023). "Bioinformatics analysis and sequence alignments performed in our laboratory proposed that miR-3174 can target many influential tumor-promoting genes involved in the pathobiology of GBM, including CD44, PLAU, MDM2, CDK6 and RHOA." (PMID 37298284, 2023). "CD44 expression in GBM cells correlates with lower survival, greater tumor proliferation, increased treatment resistance, and more invasion." (PMID 37174724, 2023). "In this regard, emerging self-assembly pH-sensitive pegylated nano drug delivery systems, namely HA-mPEG-Cis NPs, are able to target CD44-CRC-positive cells and dissolve the hydrated PEG in the acidic tumor environment." (PMID 37538108, 2023). "We observed a significant increase in CD44 and OCT3/4 levels in Delta16HER2/SIRT6-OE tumor bulk over Delta16HER2 both in terms of median fluorescence intensity (MFI), and population frequency." (PMID 38081972, 2023). "As a natural anionic polysaccharide, hyaluronic acid (HA) directly binds to CD44, and RHAMM receptors overexpressed on various tumor cell surfaces." (PMID 37376284, 2023). "The quiescent mesenchymal BCSCs, characterized as CD44+CD24− phenotype, were located at the infiltrating edge of the tumor, whereas epithelial BCSCs, characterized as ALDH+ phenotype, proliferated more actively in a more central area." (PMID 36768876, 2023). "We found that NDRG1 maintains TGFβ-induced CSCs, specifically ALDH1+ in all cell lines and CD44+/CD24- and side population in primary-tumor-derived cells." (PMID 36594086, 2023). "The reverse is also true, as TGF-β1 regulates CD44 splicing toward CD44s expression via the RNA binding protein PCBP1, thus promoting EMT and prostate-cancer-cell migration, invasion, and tumor initiation." (PMID 37958796, 2023). "Tumor size-related proteins were involved in angiogenesis (VCAN, VTN, NRP1), EMT (FN1, CD44, THBS2), and translation (EIF1AX, EIF5), further indicating the biological basis of ccRCC growth." (PMID 37460463, 2023). "Several surface markers of CSCs have been identified, including EpCAM, CD44 and CD133, which provide a possible identification method of CSCs in the tumor stroma." (PMID 36810098, 2023). "Accordingly, all four cell phenotypes were significantly enriched following culture of isolated CD133+/CD44+ PDAC cells for up to 4 days, therefore indicating their ability to establish the initial tumor heterogeneity in vitro." (PMID 36831395, 2023).